EPHB1 (EPH receptor B1)
Diseases named in the same sentence as EPHB1 in open-access papers (continued):
Sharing a sentence is not in itself a finding about the gene and the disease.
invasive carcinoma (1 paper, 2010). A carcinoma that is not confined to the epithelium, and has spread to the surrounding stroma. "Therefore, through a germline expression or functional perturbation, EPHB1 may contribute to the observed variability in the transition from an in situ lesion to an invasive carcinoma." (PMID 21124932, 2010).
Iron deficiency (1 paper, 2019). "Iron deficiency altered methylation at the genes regulating ephrin B signaling/ephrin receptor signaling (data not shown), including increased methylation at Ephb1, Itsn1, Prkar1b, and Srgap2, and decreased methylation at Arhgef15, Mknk1, and Slit3 loci." (PMID 31137889, 2019).
Liver Fibrosis (1 paper, 2023). "Taken together, our study defined neddylation as a novel modification of EphB1 and an association between EphB1 neddylation and liver fibrosis." (PMID 36834826, 2023). "To investigate the role of EphB1 in the pathogenesis of liver fibrosis, we examined its expression and post-translational modification in CCl4-induced mouse model of liver fibrosis." (PMID 36834826, 2023). "Given the important roles of Eph receptors in tissue fibrosis and the high expression of EphB1 in HCC, we therefore postulated that EphB1 would also contribute to the progression of liver fibrosis." (PMID 36834826, 2023). "In this study, we investigated the expression and roles of EphB1 in HSCs and the mouse model of liver fibrosis." (PMID 36834826, 2023). "Above all, our results suggest that neddylation modification of EphB1 enhances its kinase activity and protein stability, thereby contributing to the pathogenesis of liver fibrosis." (PMID 36834826, 2023). "In the present study, EphB1 was disclosed and validated as a novel target of neddylation in both activated HSCs and the CCl4-induced mouse model, which expands further the endogenous protein substrate spectrum of neddylation in liver fibrosis." (PMID 36834826, 2023). "It has been shown that some Eph receptors can be phosphorylated by other Eph receptors through reciprocal regulation, and whether EphB1 and EphB2 would synergistically contribute to liver fibrosis remains to be explored." (PMID 36834826, 2023). "In view of the overactivation of neddylation pathway that has been described during liver fibrosis, we were inspired to explore whether EphB1 could be conjugated to NEDD8 in HSCs." (PMID 36834826, 2023). "Our findings revealed the involvement of EphB1 in the development of liver fibrosis through its neddylation, which provides new insights into the Eph receptor signaling and a potential target for the treatment of liver fibrosis." (PMID 36834826, 2023). "However, our preliminary study showed that EphB1 was the only NEDD8-conjugated protein among EphB1 to EphB3 in activated HSCs, suggesting that the activation of EphB1 and the way it functions may be different from EphB2 in liver fibrosis." (PMID 36834826, 2023). "Hence, the inhibition of EphB1 and its neddylation could be a potential therapeutic approach for the treatment of liver fibrosis." (PMID 36834826, 2023).
lymphoma (1 paper, 2025). A malignant (clonal) proliferation of B- lymphocytes or T- lymphocytes which involves the lymph nodes, bone marrow and/or extranodal sites. "Additional eight mutations that were significantly enriched in rHL/prHL affect genes that were previously associated with the progression of other lymphoma subtypes (e.g., PDGFRB, KAT6A, HGF, EPHB1, NSD2, PMS2)." (PMID 39992429, 2025).
metabolic syndrome (1 paper, 2024). A cluster of metabolic risk factors for CARDIOVASCULAR DISEASES and TYPE 2 DIABETES MELLITUS. "The remaining ten drugged proteins were targeted by compounds indicated for treatment of cancers (CAN2, EPHB1, ERAP1, GSTM3, NQO1, and PVRL4), mitochondrial and muscular disease (NQO1), and metabolic syndrome (CEL)." (PMID 39434187, 2024).
metastatic colorectal cancer (1 paper, 2023). "We previously demonstrated reduced cell compartmentalisation for somatic EPHB1 mutations found in metastatic colorectal cancer cases." (PMID 38102712, 2023).
metastatic disease (1 paper, 2023). "In addition, EphB1 is frequently mutated in CRC, with particularly high incidence in metastatic CRC, suggesting that EphB1 mutations might have clinical relevance in predicting the development of metastatic disease." (PMID 37527777, 2023).
rhabdomyosarcoma (1 paper, 2024). A rare aggressive malignant mesenchymal neoplasm arising from skeletal muscle. "An increased expression of EPHs (EPHB1, EPHB2, EPHB3, and EPHB4) and their ephrin ligands (ephrin-B1 and ephrin-B2) has been implicated in promoting angiogenesis and tumor progression in rhabdomyosarcoma." (PMID 38612645, 2024).
vascular malformation (1 paper, 2019). A non-neoplastic disorder that is the result of defects of vascular morphogenesis. "Furthermore, whether the dysregulation of EphB1 and EfnB2 is only present in PWS or also in other types of congenital vascular malformations such as IHs is yet to be answered." (PMID 31067686, 2019).
cancer (30 papers, 2009 to 2026). A tumor composed of atypical neoplastic, often pleomorphic cells that invade other tissues. "To investigate the functional impact of the selected EPHB1 mutations in cancer development and metastasis, we used the in vitro compartmentalisation assay in human DLD-1 CRC cells." (PMID 38102712, 2023). "The expression and assay approaches we described here should be applicable to studies of other cancer-associated EphB1 mutations, although a limitation is that they would be restricted to mutations occurring within the kinase domain." (PMID 37527777, 2023). "To assess the effects of the cancer-associated EphB1 mutations in mammalian cells, we expressed the full-length WT and five cancer-associated mutant EphB1 receptors in human embryonic kidney 293T (HEK293T) cells." (PMID 37527777, 2023). "We expressed and purified the kinase domains of WT and five cancer-associated mutant EphB1 and developed assays to assess the functional effects of the mutations." (PMID 37527777, 2023). "To measure the steady-state kinetic values of the WT and cancer-associated mutant EphB1 kinases, we carried out a continuous spectrophotometric assay." (PMID 37527777, 2023). "Using the phosphocellulose binding assay with the IR peptide, we measured the activities of the WT and five cancer-associated mutant EphB1 kinases." (PMID 37527777, 2023). "The increased Tm in all five cancer-associated mutants indicated the presence of well-formed ATP binding sites in the EphB1 kinases." (PMID 37527777, 2023). "The immature T-cells, especially in subtypes AB/B1, had higher EphB6 H-score than carcinoma-associated mature lymphocytes (p < 0.001); carcinomas had higher lymphocytic EphB1 H-score (p = 0.026)." (PMID 34943502, 2021). "We also observed that EPHB1 mediated cancer-promoting traits underlying PRAD progression." (PMID 40548257, 2025). "To assess whether the cancer-associated mutations affected the stability of the folded structure of EphB1, we carried out a thermal shift assay." (PMID 37527777, 2023). "Given its association with cancer and the indication that there is a gap between available data and curated knowledge, further curation of EPHB1 and CSNK1A1L may be especially valuable." (PMID 29695735, 2018). "Thus, some of the mutations found in EPHB1 may contribute to the increased invasive capacity of cancers with mutations in the Eph receptor." (PMID 38651144, 2024). "Ligand-activated EphB1 signaling inhibits cancer cell migration and invasion through inducing EphB1 phosphorylation." (PMID 38811954, 2024). "Genes potentially associated with cell migration and cancer metastasis included CNTN5, FN1, Integrin Subunit Beta 6 (ITGB6), EPHB1, Unc-5 Netrin Receptor D (UNC5D), SDK1, RADIL, LRRC7, PCDH11X, and ADAMTS9." (PMID 39770638, 2024). "Cancer cells acquire stem cell characteristics and resistant to chemotherapy via context-dependent EphB1 signaling." (PMID 38811954, 2024). "We therefore integrated pan-cancer and pan-EPH mutational data to prioritise recurrent EPHB1 mutations for functional studies to understand their contribution to cancer development and metastasis." (PMID 38102712, 2023). "After analysing pan-cancer and pan-EPH somatic mutational data from TCGA, we identified 8 mutations in 3D-cluster pairs and 7 recurrent mutated positions in EPHB1 for further functional studies." (PMID 38102712, 2023). "The abolished cis signaling enhanced E-cadherin in the complex and the regain of cell-cell contact in MET reactivated cancer cells resulted in the activation of EphB1 trans signaling triggered by opposing cells." (PMID 36402751, 2022). "Further, we showed that EphB1 and p-EphB1 showed dynamic expression in the process of cancer cell dormancy and reactivation, where the expression profiles of EphB1 and p-EphB1 showed negatively correlated." (PMID 36402751, 2022). "The paradox roles of EphB1 on the cancer progression remind researchers the diverse function of EphB1." (PMID 36402751, 2022).
cancer (continued). "The discrepancy between EphB1 and phosphorylated EphB1 suggested that the cis signaling or trans signaling of EphB1 dominate in dormant or reactivated cancer cells." (PMID 36402751, 2022). "The treatment of EphrinB2-Fc on A549 cells transfected of Y594Δ caused reduced expression of Sox2 and Nanog compared to A549 cells transfected with EphB1 WT, confirming the role of EphB1 phosphorylation trans signal on cancer stem cell enrichment." (PMID 36402751, 2022). "On the contrary, interactions of EphB1 and ligand ephrinB2 in trans promoted the stemness of cancer cells through upregulating Sox2 during the shift from cellular dormancy to reactivation." (PMID 36402751, 2022). "On the contrary, in the state of MET, in which cell-cell adhesion was recovered, interactions of EphB1 and ligand EphrinB2 in trans promoted the stemness of cancer cells through upregulating Nanog and Sox2." (PMID 36402751, 2022). "We performed Real-time PCR to confirm the dynamic expression of EphB1 in dormant and reactivated cancer cells after chemotherapy." (PMID 36402751, 2022). "To examine the relationship between EphB1 cis- and trans- signalings and enrichment of cancer stem cells, we transfected A549 cells with EphB1 WT and mutants." (PMID 36402751, 2022). "In the majority of cases, high epithelial and variable lymphocytic EphB1 positivity was noted, the latter being more frequent in carcinomas." (PMID 34943502, 2021). "Examples include Eph‐dependent signalling in endocrine and immune systems as well as in cancer cell proliferation, where links between EphB6 and EphA10 and canonical kinases such as EphB4, EphB1 and Src‐family kinases have been established." (PMID 32053275, 2020). "In conclusion, the roles of EphB1 in cancer cell invasion and migration are context-dependent and involve the cis- or trans- interactions between receptor and ligands." (PMID 32368295, 2020). "A better understanding of context of EphB1 signaling can help to explain the paradox roles in cancer progression." (PMID 32368295, 2020). "Significant higher expression of EphB1 in cancer biopsies were found in patients with metastasis compared to non-metastatic patients with NSCLC." (PMID 32368295, 2020). "Other cancer stemness-related genes, except for EphB-1 and SMO, were downregulated to different extents by 20% to 30%, by extract or physciosporin at 10 μg/mL." (PMID 31795147, 2019). "The different roles of EphB1 in tumor development can be partially explained by the fact that the function of Eph receptors is highly context-dependent and can vary across cancer types." (PMID 28194092, 2017). "Several other interesting candidate genes were also identified such as CAMK1, STK6, PANK2 and EPHB1, all of which have been previously reported as being involved in cancer." (PMID 19519883, 2009). "EPHB1 is a member of the receptor tyrosine kinases that mediate the Eph receptor and ligand signaling transduction to regulate cell migration, differentiation, adherence, apoptosis, and proliferation in cancer." (PMID 40548257, 2025). "Furthermore, cancer cells with reduced EphB1 protein expression showed a higher capacity for tissue invasion." (PMID 38651144, 2024). "However, in the MET state, where cell–cell adhesion is regained, EphB1 and ligand ephrinB2 interactions in trans promote cancer cell stemness, affecting genes like Nanog and Sox2." (PMID 38811954, 2024). "To examine whether the crude extract and 1′-O-methyl-averantin inhibit expression of cancer stemness markers in CSC221 cells, we measured expression of mRNA encoding ALDH1, CD133, CD44, Lgr5, Msi-1, and EphB1." (PMID 36797277, 2023). "ALDH1, CD133, CD44, Lgr5, Msi-1, and EphB1 are markers of cancer stemness." (PMID 36797277, 2023). "Indeed, blocking or genetic deletion of EphB1 prevents and reverses cancer pain and morphine tolerance." (PMID 36231105, 2022).
cancer (continued). "Increased expression of EphB1 and decreased expression of p-EphB1 suggested that reduction of cell-cell contact in dormant cancer cells disrupted EphB1 trans signaling triggered by opposing cells and promoted EphB1 cis signaling which occurred in the same cells." (PMID 36402751, 2022). "The treatment of EphrinB2-Fc on A549 cells increased the ratio of CD133+ cancer stem cells and knockdown of Sox2 and Nanog by siRNA could reverse the enrichment of cancer stem cells induced by EphB1 trans signaling." (PMID 36402751, 2022). "We speculated that cell adhesion-mediated sphere formation was involved in the enrichment of cancer stem cells and cell adhesion-mediated sphere formation triggered EphB1 trans signaling." (PMID 36402751, 2022). "Furthermore, the blockade of EphB1 upregulation prevents the development of tolerance to opioids in a cancer pain model." (PMID 36231105, 2022). "We next investigated the roles of phosphorylated EphB1 in the enrichment of cancer stem cells." (PMID 36402751, 2022). "Aberrantly overexpression of EphB1 in varied of cancers leads to the hypothesis that upregulated expression of Eph receptors have functions independent of ephrins." (PMID 36402751, 2022). "The expression of EphB1 is upregulated and the nociceptive behaviors of thermal hyperalgesia and/or mechanical allodynia are induced by applying cutaneous inflammation, peripheral nerve injury, or carcinoma cells inoculation." (PMID 33880135, 2021). "EphB1 expression was significantly higher in NSCLC samples compared to non-cancer controls." (PMID 32368295, 2020). "Our findings also emphasize the potent role of EphB1 in cancer cell migration." (PMID 25879388, 2015). "These genes include tumor suppressors or candidates (VHL, CTDSPL, LRRC3B, ALDH1L1, and EPHB1) and genes that were not previously considered as cancer-associated (e.g., LRRN1, GORASP1, FGD5, and PLCL2)." (PMID 24977159, 2014). "EL001672 and 1′-O-methyl-averantin suppresses the cancer stemness markers such as ALDH1, CD44, CD133, Lgr-5, Msi-1 and EphB1." (PMID 36797277, 2023). "In our dataset, in addition to EPHB1, we also identified EPHA1, EPHA2 and EPHA7 that were highly phosphorylated in cancer compared to normal tissue, making these proteins as potential therapeutic targets." (PMID 36093296, 2022). "By accessing pan-cancer pan-EPH mutational data we selected and evaluated 15 EPHB1 mutants from which 7 lacked impact, 2 enhanced, and 6 reduced or strongly compromised cell compartmentalisation." (PMID 38102712, 2023). "We selected novel epigenetic markers including NKIRAS1/RPL15, THRB RBPS3 (CTDSPL), IQSEC1, NBEAL2, ZIC4, LOC285205, CGGBP1, EPHB1 and FOXP1 that allowed detection of cancer in ovarian biopsies on all stages with sensitivity equal to (72 ± 11)% and specificity (94 ± 5)%." (PMID 23202957, 2012).
tumor (30 papers, 2010 to 2025). "Focusing on the top six mutant genes in high-risk samples, an in vitro assay demonstrated that EPHB1 and KIF13A were significantly overexpressed in tumor cells and that low levels of EPHB1 were associated with a better prognosis." (PMID 40548257, 2025). "Conversely, overexpression of EPHB1 and ephrin-A2 is associated with a favorable prognosis, while ephrin-A5 acts as a tumor suppressor via the negative regulation of epidermal growth factor (EGFR)." (PMID 38612645, 2024). "EphB1 and EphB3 act as tumor suppressors, and their low expression is associated with metastasis and a poor prognosis." (PMID 39839790, 2024). "Together, these results demonstrate that the modulation of EphB1 function by somatic mutations can impair its tumor suppressor properties." (PMID 37527777, 2023). "To gain insight into the mechanism by which somatic mutations impair EphB1-mediated tumor suppression, we assessed their effects on kinase structure and function, using in vitro assays with purified proteins and by expression in mammalian cells." (PMID 37527777, 2023). "The adenomyoepithelioma component likely displayed intra-tumor genetic heterogeneity, given that it harbored a subclonal EPHB1 missense mutation and a subclonal TERT promoter hotspot mutation." (PMID 29739933, 2018). "EphB1/ephrins signaling is not only implicated in suppressing tumor migration and invasion, but also promoting tumor development." (PMID 28194092, 2017). "Using genetically engineered mouse models, we established that genetic loss of EphB1 resulted in a significant delay in tumor recurrence following irradiation compared to EphB1-expressing control tumors." (PMID 25879388, 2015). "Using this new model, we show that the genetic loss of EphB1 results in a significant delay in tumor recurrence following radiotherapy." (PMID 25879388, 2015). "In somatic mutation analysis, EPHB1 and KIF13A from the top six mutant genes were overexpressed in 22RV1 and PC-3 tumor cells, and low levels of EPHB1 indicated a better prognosis." (PMID 40548257, 2025). "The role of EPHB1 in tumor viability, proliferation, and invasion was analyzed using knockdown and overexpression experiments." (PMID 40548257, 2025). "Silencing EphB1 also delayed tumor recurrence after irradiation, indicating its role in cell cycle progression and resistance to therapy." (PMID 41200151, 2025). "Transcriptomic analyses revealed EphB1 enrichment in tumor spheres with high self-renewal and in migrating cells, supporting its role in motility and stemness." (PMID 41200151, 2025). "In tumors, EphB1/ephrins signaling has been shown to have a dual role, being involved in inhibiting tumor migration and invasion and promoting tumor progression." (PMID 37501725, 2023). "EphB1, the receptor of EFNB1, functioned as a tumor suppressor in AML, EphB1 repression was associated with poor prognosis of pediatric AML." (PMID 35603962, 2022). "In AML, EPHB1 has been defined as a tumor suppressor that regulates DNA damage response system; therefore, mutations affecting this gene have been correlated with poor overall survival." (PMID 30303964, 2018). "More studies are still required to comprehensively elucidate the crosstalk between EphB1 with these signaling molecules for understanding the action mechanism of EphB1 on the migration and invasion of tumor cells." (PMID 28194092, 2017). "Another future research direction will be the use of cytotoxic payloads delivered by antibody–drug conjugates to interfere with EphB1/ephrins signaling for inhibiting tumor cell growth." (PMID 28194092, 2017). "EphB1/ephrins signaling has perplexing dichotomous roles with tumor-suppressing and -promoting functions depending on the cellular context." (PMID 28194092, 2017). "Overexpression of EPHB1 increased tumor cell viability, invasion, and proliferation." (PMID 40548257, 2025).